TMEM240 (transmembrane protein 240)
Synonyms: C1orf70; SCA21
Tractability: Antibody: UniProt places it where antibodies can reach, with high confidence; UniProt predicts a signal peptide or a membrane-spanning region; its Gene Ontology location is reachable by antibodies, with medium confidence.
Gene: Protein-coding gene on chromosome 1 (1,534,778 to 1,540,624, reverse strand). Ensembl gene ENSG00000205090.
Subcellular location: Synapse; Cell membrane
Gene Ontology:
Cellular component: synaptic membrane; cerebellar climbing fiber to Purkinje cell synapse; parallel fiber to Purkinje cell synapse; plasma membrane; postsynaptic density membrane; synapse; TMEM240-body
Genetic constraint (gnomAD): Loss-of-function variants: 3 observed, 15.64 expected, observed/expected ratio (o/e) 0.19, 90% interval 0.086 to 0.5. The upper end of that interval is the gene's LOEUF score, 0.5, which puts it in group 2 of 6, group 1 being the genes least tolerant of losing a copy. Missense variants: 210 observed, 242.38 expected, observed/expected ratio (o/e) 0.87, 90% interval 0.77 to 0.97. Synonymous variants: 123 observed, 107.66 expected, observed/expected ratio (o/e) 1.14, 90% interval 0.99 to 1.33.
Homologues: Orthologues: chimpanzee TMEM240 (100% identical), macaque C1orf70 (99% identical), guinea pig TMEM240 (98% identical), mouse Tmem240 (98% identical), pig TMEM240 (98% identical), dog TMEM240 (95% identical), zebrafish tmem240a (82% identical), rat Tmem240 (75% identical), tropical clawed frog tmem240 (71% identical), zebrafish tmem240b (54% identical).